RNU7-22P (RNA, U7 small nuclear 22 pseudogene)
Synonyms: U7.22
Gene: Small nuclear RNA gene on chromosome 10 (32,173,684 to 32,173,744, forward strand). Ensembl gene ENSG00000252482.
Homologues: Orthologues: macaque U7 (95% identical). Paralogues in human: RNU7-6P (93% identical), RNU7-11P (92% identical), RNU7-13P (92% identical), RNU7-28P (92% identical), RNU7-3P (92% identical), RNU7-25P (90% identical), RNU7-41P (90% identical), RNU7-7P (90% identical), RNU7-8P (90% identical), RNU7-14P (89% identical), RNU7-18P (89% identical), RNU7-40P (89% identical), and 142 more.